JHY (junctional cadherin complex regulator)
Description:
Required for the normal development of cilia in brain ependymal cells lining the ventricular surfaces.
Synonyms: C11orf63; FLJ23554
Tractability: Antibody: its Gene Ontology location is reachable by antibodies, with medium confidence.
Gene: Protein-coding gene on chromosome 11 (122,882,683 to 122,963,865, forward strand). Ensembl gene ENSG00000109944.
Subcellular location (Human Protein Atlas): Nucleoplasm; Golgi apparatus
Gene Ontology:
Biological process: axoneme assembly; brain development
Genetic constraint (gnomAD): Loss-of-function variants: 66 observed, 77.96 expected, observed/expected ratio (o/e) 0.85, 90% interval 0.69 to 1.04. The upper end of that interval is the gene's LOEUF score, 1.04, which puts it in group 4 of 6, group 1 being the genes least tolerant of losing a copy. Missense variants: 905 observed, 927.58 expected, observed/expected ratio (o/e) 0.98, 90% interval 0.92 to 1.03. Synonymous variants: 356 observed, 344.8 expected, observed/expected ratio (o/e) 1.03, 90% interval 0.95 to 1.13.
Homologues: Orthologues: chimpanzee JHY (98% identical), macaque JHY (93% identical), pig JHY (76% identical), dog JHY (74% identical), rabbit JHY (71% identical), mouse Jhy (67% identical), rat Jhy (66% identical), guinea pig JHY (58% identical), zebrafish jhy (21% identical).
Diseases named in the same sentence as JHY in open-access papers:
JHY is named in the same sentence as 2 diseases in open-access papers, as found by Europe PMC text mining. Sharing a sentence is not in itself a finding about the gene and the disease. The quoted sentences say what the papers report.
cancer (2 papers, 2021 to 2026). A tumor composed of atypical neoplastic, often pleomorphic cells that invade other tissues. "The model identified key genes such as C3orf36, JHY, and TASP1, showing significant differences in mutation counts across cancers." (PMID 41870130, 2026). "Many of the genes such as JHY, PLAAT1, PNMA8B, RPL37P6, SNX32, UGGT2 and Y_RNA have not been related to any cancer, yet." (PMID 33672117, 2021).
JHY also shares sentences with these, for which no sentence is quoted: endometrial cancer (1 paper).